SNHG12 (small nucleolar RNA host gene 12)
Diseases named in the same sentence as SNHG12 in open-access papers (continued):
Sharing a sentence is not in itself a finding about the gene and the disease.
cervical cancer (15 papers, 2019 to 2025). A primary or metastatic malignant neoplasm involving the cervix. "Recent studies have highlighted the significant upregulation of lncRNA SNHG12 in ovarian and cervical cancers, where its suppression has been shown to markedly reduce tumor cell proliferation, migration, and invasion." (PMID 38566229, 2024). "Another study indicated that SNHG12 plays a significant regulatory role in the progression of cervical cancer by modulating the miR-125b/STAT3 axis." (PMID 38566229, 2024). "Association of SNHG12 expression level with advanced FIGO stage, vascular involvement, and lymph node metastasis in cervical cancers evidenced its potential clinical significance." (PMID 35406435, 2022). "Knockdown of SNHG12 plays a role in cervical cancer by increasing the expression of miR-148a, which can be reversed by miR-148a inhibitors." (PMID 35692795, 2022). "Dong showed that lncRNA nuclear RNA host gene 12 (SNHG12) was abnormally elevated in human cervical cancer tissue, while silencing SNHG12 inhibited the proliferation of cervical cancer cells and tumor growth in a nude mouse model." (PMID 35409396, 2022). "Significantly higher expression levels of SNHG12 were described in hepatocellular, papillary thyroid, and cervical carcinomas compared to normal tissues, among other cancer types." (PMID 35406435, 2022). "Previously, SNHG12 was also reported to act as a ceRNA in several tumors, such as cervical cancer and oral squamous cell carcinoma." (PMID 34239888, 2021). "For example, functional assays have shown that inhibition of SNHG12 expression decreased cell proliferation both in vitro and in vivo, indicating that SNHG12 plays a critical role in the progression of cervical cancer." (PMID 33803022, 2021). "In cervical cancer, SNHG12 was shown to exhibit a high level, and its knockdown was observed to modulate the radiosensitivity of cervical cancer via upregulating CDK1 expression through sponging miR-148a." (PMID 34239888, 2021). "In cervical cancer, SNHG12 promotes proliferation, invasion, and migration, by targeting miR-424-5p." (PMID 32318335, 2020). "It is reported that SNHG12 accelerates the tumorigenesis of prostate cancer via sponging miR-133b and promotes the progression of the cervical cancer via modulating miR-125b/STAT3 axis." (PMID 31824846, 2019). "In an in vivo study, knockdown of SNHG12 resulted in smaller tumor volumes and reduced tumor weights in CaSki cervical cancer cell-derived human xenografts in nude mice compared to the control mice." (PMID 31620362, 2019). "Taken together, these data suggested that SNHG12 plays an important role in promoting tumorigenesis and metastasis in cervical cancer via sponging of miRNAs, such as miR-125p and miR-424-5b." (PMID 31620362, 2019). "Similarly, SNHG12 was overexpressed in both cervical cancer tissues and cells, and was positively correlated with tumor size and TNM stage." (PMID 35692795, 2022). "However, miR-148a inhibitor and CDK1 overexpression can reverse the effects of SNHG12 gene knockout on the radiosensitivity of cervical cancer cells." (PMID 35692795, 2022). "Interestingly, however, the expression of SNHG12 in tumor tissues and cells after radiotherapy was significantly lower than that before treatment, suggesting that SNHG12 may be related to the radiotherapy sensitivity of cervical cancer." (PMID 35692795, 2022).
breast carcinoma (11 papers, 2017 to 2024). "SNHG12 was highly expressed in breast cancer cell-derived exosomes and HUVECs co-cultured with exosomes, indicating that exosomal SNHG12 is an important molecule in angiogenesis." (PMID 38833118, 2024). "Taken together, these findings suggest that breast cancer cell-derived exosomal SNHG12 was a key target for cancer therapy." (PMID 38833118, 2024). "In conclusion, our findings demonstrated that exosomal SNHG12 regulates HUVEC angiogenesis to promote breast cancer progression by interacting with PBRM1 to target MMP10." (PMID 38833118, 2024). "We demonstrated that SNHG12 was highly expressed in both breast cancer cells and their secreted exosomes, promoting HUVEC angiogenesis and tumor progression via PBRM1 and MMP10." (PMID 38833118, 2024). "C-Myc-induced upregulation of SNHG12 was shown to support breast cancer cell proliferation and migration." (PMID 35328609, 2022). "In fact, SNHG12 upregulation promotes proliferation, inhibits apoptosis, and induces breast cancer cell migration whereas SNHG12 silencing inhibits breast cancer cell growth in vitro and in vivo." (PMID 36139687, 2022). "SNHG12 was reported to increase in breast cancer tissues and cells and correlate with cancer progression." (PMID 35328609, 2022). "SNHG12 was also clarified to promote cell migration by regulating MMP13 expression in breast cancer." (PMID 29137407, 2017). "SNHG12 levels were down‐regulated significantly in human breast cancer cell lines, suggesting that the decrease in SNHG12 expressions might play important roles in the oncogenesis." (PMID 28941134, 2018). "Exosomal SNHG12 may be a novel therapeutic target for breast cancer." (PMID 38833118, 2024). "In summary, our findings confirmed that exosomal SNHG12 promoted HUVEC angiogenesis via the PBRM1-MMP10 axis, leading to enhanced malignancy of breast cancer." (PMID 38833118, 2024). "Combining exosomal sequencing results with The Cancer Genome Atlas Breast Cancer database, we screened lncRNA small nucleolar RNA host gene 12 (SNHG12), which was highly expressed in breast cancer cells." (PMID 38833118, 2024).
lung cancer (11 papers, 2019 to 2025). A malignant neoplasm involving the lung. "SNHG12 overexpression predicted poor prognosis in prostate cancer, while it was associated with tumor progression and poor survival rates in gastric and lung cancer." (PMID 35406435, 2022). "MiR‐181a is sponged by small nucleolar RNA host gene 12 (SNHG12), a lncRNA that is overexpressed in lung cancer and inversely correlated with miR‐181a levels." (PMID 30548184, 2019). "However, it is recognized that the SNHG12 knockdown can reverse the resistance to cisplatin, paclitaxel, and gefitinib in cell lines derived from lung cancer." (PMID 35406435, 2022). "The upregulated SNHG12 confers resistance to gefitinib in lung cancer cells." (PMID 33931980, 2021). "Furthermore, SNHG12 is transported to lung cancer cells from CAFs through EVs." (PMID 39717771, 2024). "The internalization of CAF-origin EVs by lung cancer cells results in elevated MEG3 and SNHG12 levels, conferring cisplatin resistance." (PMID 39717771, 2024). "In non‐small cell lung cancer (NSCLC), SNHG12 modulates multidrug resistance via sponging miR‐181a and activating MAPK/Slug pathway." (PMID 33787057, 2021). "LncRNA NNT antisense RNA 1 (NNT‐AS1) and small nucleolar RNA host gene 12 (SNHG12) have been shown to upregulate the EMT‐related transcription factor Slug through the MAPK/ERK signaling pathway to promote EMT, making lung cancer cells resistant to chemotherapy." (PMID 33931980, 2021).
glioblastoma (10 papers, 2020 to 2023). The most malignant astrocytic tumor (WHO grade IV). "Small nucleolar RNA host gene 12 (SNHG12) is an oncogenic lncRNA, which is aberrantly expressed in temozolomide-resistant glioblastoma cells and tissues." (PMID 33806782, 2021). "DNA-methylation-mediated activation of SNHG12 promoted temozolomide resistance in glioblastoma." (PMID 35721492, 2022). "CpG methylation in the promoter region of SNHG12 promotes the competitive binding of SNHG12 with miR-129-5p, regulates the MAPK/ERK pathway and G1/S cell cycle transition, thereby affecting the resistance of glioblastoma cells to temozolomide." (PMID 35597996, 2022). "In temozolomide-sensitive glioblastoma cell, the CGI hypermethylation of SNHG12 promoter blocked the occupancy of SP1 and inhibited the expression level of SNHG12." (PMID 34175894, 2021).
lymph node metastasis (10 papers, 2019 to 2025). "Increased levels of SNHG12 were found to be associated with clinicopathological manifestations such as lymph node metastasis, and International Federation of Gynecology and Obstetrics (FIGO) stage, where high-grade tumors (stage II) showed increased expression compared to low-grade tumors (stage I)." (PMID 31620362, 2019). "Results of the present study revealed that high SNHG12 expression levels are associated with TAM2 infiltration, lymph node metastasis and poor long-term survival rates in patients with NSCLC." (PMID 40417819, 2025). "High expression of SNHG12 was correlated with an aggressive phenotype in patients evidenced by higher Gleason score and lymph node metastasis." (PMID 35159022, 2022). "SNHG12 high expression is related to the OS, tumor stage, lymph node metastasis, tumor size, distant metastasis, and high tumor grade, especially in the Chinese population." (PMID 34372942, 2021). "Additionally, higher expression of SNHG12 suggested unfavorable clinicopathological outcomes including larger tumor size, lymph node metastasis, distant metastasis, and advanced clinical stage." (PMID 33124951, 2020). "Besides, Chi-square test results suggested that there was a correlation between lymph node metastasis and the expression level of SNHG12 (p <0.05)." (PMID 31824846, 2019). "Results of the present study also indicated that SNHG12 expression was significantly increased in patients with NSCLC and lymph node metastasis." (PMID 40417819, 2025). "The high expression of SNHG12 positively correlated with PSA, Gleason score, lymph node metastasis, and advanced residual tumour grade, as well as poor prognosis of PCa patients, suggesting potential utility as a PCa prognostic biomarker." (PMID 35159022, 2022). "In this study, we also confirmed that SNHG12 was highly expressed in GC cell lines and tissues and that its high expression was clinically closely related to the invasion depth, TNM stage and the extent of lymph node metastasis." (PMID 33994849, 2021). "In addition, SNHG12 had no significant relation with patient sex and age, but had significant association with tumor grade, TNM stage, and lymph node metastasis." (PMID 35597996, 2022).
ovarian carcinoma (10 papers, 2019 to 2025). A malignant neoplasm originating from the surface ovarian epithelium. "In this study, we performed gain- and loss- of function experiments to reveal the role of the small nucleolar RNA host gene 12 (SNHG12) in immune escape by generating the crosstalk between ovarian cancer cells and M2 macrophages." (PMID 32927431, 2020). "In our study, upregulated SNHG12 may have participated in the underlying mechanisms of platinum resistance in ovarian cancer patients by targeting miR-320b and miR-320d." (PMID 35592674, 2022). "SNHG12 gene silencing increased the sensitivity to carboplatin, giving evidence that this lncRNA contributes to resistance to carboplatin in ovarian cancer cell lines." (PMID 35406435, 2022). "In this study, we constructed the lncRNA-mediated ceRNA networks to reveal that miR-320b and miR-320d were probably involved in the mechanisms of platinum resistance in ovarian cancer patients mediated by SNHG12, MEG3, and NR2F1-AS1." (PMID 35592674, 2022). "SNHG12 facilitated ovarian immune escape by promoting IL-6/miR-21 crosstalk between ovarian cancer cells and M2 macrophages." (PMID 32927431, 2020). "Meanwhile, SNHG12 and IL-6R expressions were positively correlated in clinical ovarian cancer samples." (PMID 32927431, 2020). "Sun and Fan reported that SNHG12 was up-regulated (~1.7-fold) in ovarian cancer (OC) tissues as compared to the normal adjacent tissues, and a similar expression was observed in OC cell lines as compared to a normal ovarian epithelial cell line." (PMID 31620362, 2019). "Interestingly, SNHG12 can promote the expression of the transcription factor SOX4 in ovarian cancer tissues and increase the proliferation and migration of tumor cells." (PMID 41200835, 2025). "Likewise, the lncRNA SNHG12 (small nucleolar RNA host gene 12) was found as overexpressed in several types of cancer including ovarian cancer." (PMID 34204094, 2021). "Consistent with our in vitro data, SNHG12 was also found to be highly expressed in ovarian cancer clinical samples, suggesting that SNHG12 may be a promising biomarker for ovarian cancer diagnosis." (PMID 32927431, 2020). "Based on the findings presented above, we next set out to determine whether SNHG12 played a role in ovarian cancer cell immune escape, mediated by the IL-6/miR-21 feedback loop." (PMID 32927431, 2020). "Furthermore, it was also showed that SNHG12 exerted its carcinogenic effects by interacting with miR-129 and upregulating the expression of SOX4 and thereby promoted ovarian cancer progression." (PMID 33294456, 2020).
endometrial carcinoma (9 papers, 2017 to 2025). A malignant tumor arising from the epithelium that lines the cavity of the uterine body. "Suppressing SNHG12 can cause the repression of cell proliferation, increased apoptosis, and G1 phase arrest in endometrial cancer." (PMID 28793054, 2017). "Small nucleolar RNA host gene 12 (SNHG12), also referred to as ASLNC04080 is a novel lncRNA located on chromosome 1p35.3 that was initially found to be increased within endometrial carcinoma." (PMID 38946724, 2024). "Small nucleolar RNA host gene 12 (SNHG12) is a lncRNA located at chromosome 1p35.3 and was originally reported to be overexpressed in endometrial cancer." (PMID 33294456, 2020). "SNHG12 was first identified to be significantly upregulated in endometrial cancer, and inhibition of SHNG12 expression led to proliferation suppression and apoptosis induction in endometrial cancer cells." (PMID 29137407, 2017). "In endometrial carcinoma, a distinct regulatory pattern was observed, with LINC00582, LINC-ROR, MEG3, NEAT1, and SNHG12 displaying significant negative correlations." (PMID 41303609, 2025).
prostate carcinoma (8 papers, 2019 to 2024). A carcinoma that arises from epithelial cells of the prostate gland. "For instance, prostate cancer patients with high SNHG12 expression were more prone to higher serum prostate-specific antigen (PSA) value, residual tumor, and bone metastasis." (PMID 33124951, 2020). "Two independent studies have shown that SNHG12 levels were up-regulated (~1.8-fold) in paired human prostate cancer (PCa) tissue samples compared to normal adjacent tissue, and (~2.3-fold) in the DU145 prostate cancer cell line compared to normal prostate cells." (PMID 31620362, 2019).
triple-negative breast carcinoma (8 papers, 2017 to 2024). An invasive breast carcinoma which is negative for expression of estrogen receptor (ER), progesterone receptor (PR), and human epidermal growth factor receptor 2 (HER2). "In another study, the small nucleolar RNA host gene 12 (SNHG12) was identified to be highly expressed in triple-negative breast cancer cells (TNBCs) and also in their secreted exosomes." (PMID 39585046, 2024). "Another study demonstrated that c-MYC-induced SNHG12 upregulation promoted cell proliferation and suppressed apoptosis in triple-negative breast cancer." (PMID 29137407, 2017). "Of note, SNHG12 is a downstream target gene of the oncoprotein MYC and its upregulation mediates cell proliferation and migration in triple-negative breast cancer." (PMID 35406435, 2022). "SNHG12 is induced by c-MYC and regulates cell proliferation, apoptosis, and migration in triple negative breast cancer." (PMID 29757368, 2018).
atherosclerosis (7 papers, 2021 to 2024). A disease characterized by the build-up of fatty material and calcium deposition in the arterial wall resulting in partial or complete occlusion of the arterial lumen. "Injecting SNHG12 has been found to help prevent atherosclerosis by protecting blood vessels from DNA damage and slowing endothelial aging." (PMID 39458994, 2024). "Studies have shown that lncRNA SNHG12 is highly expressed in vascular endothelium but decreases as atherosclerosis progresses." (PMID 39458994, 2024). "Evaluation of published RNA-Seq data using Ingenuity Pathway Analysis (IPA) from earlier work on SNHG12 in our laboratory showed that VEGF is likely a critical node in mediating the effects of SNHG12 on atherosclerosis." (PMID 34793334, 2022). "SNHG12, a long noncoding RNA (lncRNA) dysregulated in atherosclerosis, is known to be a key regulator of vascular senescence in endothelial cells (ECs)." (PMID 34793334, 2022). "SNHG12 has been shown to be protective against atherosclerosis via its role in DNA damage repair, whereas knockdown of SNHG12 exacerbated aortic atherosclerosis." (PMID 34793334, 2022). "For example, administration of NR in food fully attenuated the increases in DNA damage, endothelial senescence, and lesion formation mediated by Snhg12 knockdown in the vessel wall in a mouse model of atherosclerosis." (PMID 34220553, 2021). "Given the role of SNHG12 in atherosclerosis and its importance in vascular EC senescence, we hypothesized that SNHG12 may play a role in angiogenesis." (PMID 34793334, 2022). "The knockdown of SNHG12, highly expressed in the vascular endothelium, could accelerate atherosclerosis." (PMID 33630421, 2021). "In cardiovascular‐related studies, SNHG12 could interact with DNA‐dependent protein kinase (DNA‐PK) and IGF2BP3 and play a protective role in atherosclerosis and angiogenic endothelial cells' response to ischemia." (PMID 38946724, 2024).
colorectal cancer (7 papers, 2017 to 2022). A primary or metastatic malignant neoplasm that affects the colon or rectum. "The same tumor promoter role was observed in colorectal cancer cells, where overexpression of SNHG12 facilitates cell growth and inhibits apoptosis." (PMID 30654440, 2019). "SNHG12 is involved in both gastric and colorectal cancer, with two currently known m5C positions in its structure." (PMID 30654440, 2019). "Our results suggest that SNHG12 promoted cell growth and inhibited cell apoptosis in CRC cells, indicating that SNHG12 might be a useful biomarker for colorectal cancer." (PMID 28225893, 2017). "However, the exact expression pattern of small nucleolar RNA host gene 12 (SNHG12) in colorectal cancer and its clinical significance remains unclear." (PMID 28225893, 2017).
non-small cell lung carcinoma (7 papers, 2020 to 2024). A group of at least three distinct histological types of lung cancer, including non-small cell squamous cell carcinoma, adenocarcinoma, and large cell carcinoma. "This study was conducted with the aim of exploring the molecular mechanism of lncRNA small nucleolar RNA host gene 12 (SNHG12) in immune escape of non-small cell lung cancer (NSCLC)." (PMID 35658874, 2022). "SNHG12 overexpression promoted cell invasion, migration, and EMT in non-small cell lung cancer via engaging into Slug/ZEB signaling pathway to regulate expression of E-cadherin, matrix metalloproteinase 9 (MMP-9) and vimentin." (PMID 33124951, 2020).